GPC3 (glypican 3)
Diseases named in the same sentence as GPC3 in open-access papers (continued):
Sharing a sentence is not in itself a finding about the gene and the disease.
hepatocellular carcinoma (continued). "For example, Glypican-3 (GPC3)-targeted CAR-NK cells exhibited specific cytotoxicity against GPC3-expressing hepatocellular carcinoma cells in both in vitro and in vivo models, showing resistance to immunosuppressive factors in the tumor microenvironment." (PMID 40672956, 2025). "This study successfully developed a novel bispecific antibody (BsAb) platform targeting CD16A on NK cells and GPC3 in hepatocellular carcinoma (HCC), demonstrating three key innovations." (PMID 40574860, 2025). "The DNAM1 and 2B4 costimulatory domains also improved the cytotoxicity of anti-GPC3 CAR-NK cells in vitro against hepatocellular carcinoma cells." (PMID 40705122, 2025). "In this study, the authors showed that the GPC3-targeting immunotoxin HN3-mPE24 induced potent cytotoxicity in GPC3-positive hepatocellular carcinoma (HCC) cells, confirming its therapeutic potential." (PMID 41303525, 2025). "In one patient with advanced hepatocellular carcinoma, treatment with anti-GPC3 CAR-T cells resulted in complete tumor disappearance within 30 days following intratumoral injection." (PMID 41154636, 2025). "During the ATHENA clinical trial, investigators evaluated a CAR-T cell therapeutic agent targeting the GPC3 antigen (AZD5851) in patients with advanced or recurrent hepatocellular carcinoma." (PMID 41154636, 2025). "For example, glypican-3–specific CAR Vδ1 T cells with co-expressed IL-15 demonstrated enhanced anti-tumor activity against hepatocellular carcinoma, showing robust expansion and in vivo efficacy." (PMID 40148988, 2025). "Binding of the radiolabeled chelator-substituted TJ12P2(Q11/K11) and nanobody to human hepatoma cells with high GPC3 expression was investigated via real-time radioligand binding." (PMID 41304901, 2025). "GPC3 is a glycoprotein expressed in most hepatocellular carcinoma (HCC) patients with minimal expression in normal and cirrhotic liver tissue, making it a suitable target for CAR-T cell therapy." (PMID 40974479, 2025). "Advances in solid tumor targeting continue to expand the repertoire of actionable antigens, including glypican-3 (GPC3) in hepatocellular carcinoma, Claudin18.2 in gastric cancer, mesothelin (MSLN), and B7-H3 across various malignancies." (PMID 41394856, 2025). "A hepatocellular carcinoma targeted probe was developed by glypican-3 (GPC3)-specific aptamer (AP613-1) and USPIO (Apt-USPIO)." (PMID 38191388, 2024). "This indicates that GPC3 serve as an important target for the treatment of hepatocellular carcinoma." (PMID 39136031, 2024). "fabricated silver shell-coated magnetic nanoparticles functionalized with anti-ASGPR antibody and Au@Ag nanorods functionalized with anti-GPC3 for detection of CTCs from hepatocellular carcinoma (HCC)." (PMID 38811455, 2024). "GPC3 plays a role in the progression of hepatocellular carcinoma by interacting with Wnt signaling proteins and growth factors." (PMID 38473810, 2024). "These T cells exhibited the capability to eradicate GPC3-expressing hepatoma cells in vitro and hinder the progression of HCC xenograft tumors in mice." (PMID 39569202, 2024). "This discovery has propelled further development of GPC3 CAR-T cell therapy for hepatocellular carcinoma." (PMID 39136031, 2024). "Another possible target for CAR-T cell therapy is glypican-3 (GPC3), which is expressed in hepatocellular carcinoma (HCC)." (PMID 38892913, 2024). "In contrast, immunohistochemical staining for hepatocellular carcinoma would typically be positive for arginase 1, gpc3 hepatocytes, and AFP, and for cholangiocellular carcinoma, it would be positive for CK19 and CK8." (PMID 39099991, 2024). "Studies have shown that GPC3 is a reliable marker for hepatocellular carcinoma, with a sensitivity and specificity exceeding those of the alpha-fetoprotein and hepatocyte paraffin tests." (PMID 38919533, 2024). "Clinical trials are underway investigating GPC3 as a therapeutic target in hepatocellular carcinoma and a number of pediatric cancers." (PMID 39598037, 2024).
hepatocellular carcinoma (continued). "Numerous studies have demonstrated that higher GPC3 expression in hepatocellular carcinoma correlates with poorer prognosis." (PMID 39136031, 2024). "Vaccination with GPC3 peptides has demonstrated safe and specific immune responses, and prolonged recurrence-free survival in patients with hepatocellular carcinoma in a phase I and II clinical trial." (PMID 38727261, 2024). "GPC3, a member of the glypican family, is typically expressed in embryonic tissues and various organs, and is notably overexpressed in hepatocellular carcinoma." (PMID 39777262, 2024). "Proteomic and Transcriptomic studies in a number of cancer types have displayed an upregulation of GPC-3 expression, suggesting GPC-3 to be a useful marker for hepatocellular carcinoma (HCC)." (PMID 38894719, 2024). "Similar to Innate Pharma’s ANKETTM platform, Cytovia Therapeutics has leveraged its FLEX-NK platform to engineer CYT-303 and CYT-338 NKCEs, targeting the CD38 antigen for hematological malignancies and GPC-3 for hepatocellular carcinoma." (PMID 39911822, 2024). "Targeted immunotherapy in hepatocellular carcinoma holds considerable potential, particularly with GPC3-specific CAR-NK cells." (PMID 38694508, 2024). "The proposed strategy endows NK cells with a tumor-specific targeting ability to enhance adoptive therapeutic efficiency in GPC3+ hepatocellular carcinoma." (PMID 37665421, 2023). "Glypican-3 (GPC3) is an oncofetal antigen that is highly expressed in multiple solid tumors, including hepatocellular carcinoma, and is barely expressed in adult normal tissues except the placenta." (PMID 37048069, 2023). "Glycoproteins: Glypican-3 (GPC3) is a cell surface glycoprotein that is highly expressed in hepatocellular carcinoma cells." (PMID 38067167, 2023). "In other areas of study, researchers have also used mesoporous silica containing IR780 NPs with CAR‐T cell membranes to specifically target GPC3‐expressing hepatocellular carcinoma (HCC) cells." (PMID 37206213, 2023). "As a proof of principle, we designed genetically fused hGC33 scFv‐melittin anchored on cellular MVs targeted to GPC3‐positive hepatocellular carcinoma (HCC)." (PMID 38023709, 2023). "In another example, an affinity-tuned, mouse cross-reactive GPC3 CAR-T was able to avoid lethal toxicity against GPC3 expressed in the mouse lung and induce regression of human hepatocellular carcinoma tumors." (PMID 38090585, 2023). "GPC3 is a cell surface protein highly expressed in hepatocellular carcinoma (HCC) but barely expressed in normal liver tissue." (PMID 38045827, 2023). "The results of the modified aptamer showed significant antitumor effects against tumors GPC3-positive, suggesting that this strategy represents a promising treatment for hepatocellular carcinoma." (PMID 34844535, 2023). "The efficacy of these engineered T cells are being evaluated in two ongoing clinical trials (NCT02932956 and NCT02905188) for GPC3+ liver cancer and hepatocellular carcinoma." (PMID 37064017, 2023). "Malignant melanoma expressed HMB45, MelanA, and S-100; small cell lung cancer expressed TTF-1, CD56, and CgA; hepatocellular carcinoma expressed GPC-3, hepatocyte, and Sall4; breast cancer expressed ER, PR, Her-2, and GCDFP-15." (PMID 37608278, 2023). "This also confirm the previous studies for that GPC3 is also up-regulated in the serum of hepatocellular carcinoma, which imply that GPC3 can be a biomarker for effective diagnosis of hepatocellular carcinoma." (PMID 37036308, 2023). "Malignant melanoma expressed HMB45, MelanA, and S-100; small cell lung cancer expressed TTF-1, CD56, and CgA; hepatocellular carcinoma expressed GPC-3, hepatocyte, and Sall4." (PMID 37608278, 2023). "Glypican-3 (GPC3), as an emerging biomarker, has been shown to be beneficial for the early diagnosis and treatment of hepatocellular carcinoma (HCC)." (PMID 36903516, 2023).
hepatocellular carcinoma (continued). "Previously, GPC3 targeted immunotherapy strategy using antibody or peptide vaccine has been developed for the treatment of hepatocellular carcinoma." (PMID 37036308, 2023). "More recently, CAR‐T cells targeting glypican‐3 (GPC3) were reported to treat GPC3‐positive hepatocellular carcinoma (HCC) in clinical trials (NCT02715362, NCT03198546, and NCT02905188)." (PMID 37933232, 2023). "Noninvasively assessing the tumor biology and microenvironment before treatment is greatly important, and glypican-3 (GPC-3) is a new-generation immunotherapy target for hepatocellular carcinoma (HCC)." (PMID 36824129, 2023). "Glypican-3 is the cellular membrane proteoglycan and is regarded as a tumor biomarker for diagnosing hepatocellular carcinoma." (PMID 36910146, 2023). "GPC-3, a membrane-bound heparin sulfate proteoglycan belonging to the glycoprotein family, is over-expressed in up to 80% of patients with hepatocellular carcinoma and can distinguish liver cancer from other malignancies." (PMID 37575092, 2023). "A preclinical study focusing on glypican-3 (GPC3) CAR T cell therapy in patients with hepatocellular carcinoma demonstrated survival rates of 50%, 42%, and 10% at 6 months, 1 year, and 3 years, respectively." (PMID 37998743, 2023). "GPC3 was found to be elevated in the serum of hepatocellular carcinoma patients, which plays a crucial role in inducing cell proliferation." (PMID 38067167, 2023). "For example, CXCR2-modified GPC3-CART had improved trafficking in a hepatocellular carcinoma model, while a CXCR1/2-modified CD70-CART enhanced CART trafficking and efficacy in murine GBM, ovarian cancer and pancreatic cancer models." (PMID 35273619, 2022). "Glypican-3 (GPC3) expression is investigated as a promising target for tumor-specific immunotherapy of hepatocellular carcinoma (HCC)." (PMID 36518314, 2022). "GPC3 is an heparan sulfate proteoglycan which is expressed in embryonic tissues and solid cancers such as hepatocellular carcinoma, ovarian clear cell carcinoma, melanoma, squamous cell carcinoma of the lung, and some pediatric cancers." (PMID 35937502, 2022). "High levels of GPC3 in serum have been shown to be a marker for hepatoblastoma and hepatocellular carcinoma." (PMID 35233466, 2022). "Glypican-3 (GPC3) has become a compelling target for immunotherapy of hepatocellular carcinoma, including antibody-drug conjugate (ADC), and ADC-like immunotoxin." (PMID 35281879, 2022). "Although no GPC3 mutations have been identified so far in MCPyV-negative MCCs, GPC3 was shown to be a transcriptional target of c-Myc in the setting of hepatocellular carcinoma." (PMID 35937502, 2022). "The genes miR-4510 and glypican-3 (GPC3) have reported to be closely associated with tumors, with miR-4510 inversely correlated with GPC3 mRNA and protein in hepatocellular carcinoma samples." (PMID 35050429, 2022). "In this regard, overexpression of GPC3 was found in hepatocellular carcinoma, yolk sac tumours, clear cell ovarian carcinoma, and embryonal cancers, including neuroblastoma, Wilms’ tumour, and hepatoblastoma." (PMID 36676710, 2022). "On the other hand, GPC3 evokes EMT in hepatocellular carcinoma, thereby displaying a tissue-specific dual role." (PMID 36358747, 2022). "For example, the GPC3xCD47 BsAb targets the TAA GPC3, expressed on hepatocellular carcinoma (HCC) cells, and CD47, as well as FcγRs via a functional IgG1 Fc tail." (PMID 35884427, 2022). "In our study, GPC3 expression was associated with death from MCC, in line with reports of its prognostic role in hepatocellular carcinoma." (PMID 35937502, 2022). "RNAscope improves Glypican3 (GPC3) and glutamine synthetase (GS) specificity and sensitivity by 20-30% in hepatocellular carcinoma." (PMID 35027056, 2022). "Cell surface expression of tumor antigen GPC3 was observed by immunohistochemical staining in tumor biopsies from hepatocellular carcinoma, liposarcoma, squamous lung cancer, and Merkel cell carcinoma patients." (PMID 35507536, 2022).
hepatocellular carcinoma (continued). "The authors genetically modified CAR-T cells via lentivirus transfection to enable targeting of glypican-3 (GPC3) proteoglycans that are overexpressed by GPC3 + hepatocellular carcinoma cells." (PMID 35960404, 2022). "For this study, we employed Ad-IL-12 and Ad-GPC3 to determine their anti-tumor effects on hepatoma cells." (PMID 36139670, 2022). "Some cancers have several studies with the same target, such as hepatocellular carcinoma with GPC3, pancreatic cancer with MSLN, and glioma with GD2." (PMID 35681646, 2022). "GPC3 is often observed to be highly elevated in hepatocellular carcinoma and is a target for diagnosis and treatment of hepatocellular carcinoma." (PMID 35931322, 2022). "Glypican 3 (GPC3) was potential immune target for hepatocellular carcinoma through fusing to alpha epitope of HBsAg." (PMID 34025929, 2021). "A similar positive feedback signaling loop of GPC3 and c-Myc has been demonstrated in hepatocellular carcinoma; c-Myc upregulated the expression of GPC3 by binding to its c-Myc-binding sites in the GPC3 promoter, while GPC3 elevated the expression of c-Myc48." (PMID 33712571, 2021). "Glypican-3 (GPC3) is a cell surface heparan sulfate proteoglycan that is being evaluated as an emerging therapeutic target in hepatocellular carcinoma (HCC)." (PMID 33420124, 2021). "CARs specific to GPC3 are undergoing clinical evaluation in patients with hepatocellular carcinoma and lung squamous cell carcinoma." (PMID 34839348, 2021). "Arg-1 and GPC-3 have been extensively used to differentiate hepatocellular carcinoma cells from cholangiocarcinoma and metastatic tumor cells in the liver because of their sensitivity." (PMID 34715880, 2021). "Accumulating evidence indicates that GPC3 activates the canonical Wnt signaling pathway in hepatocellular carcinoma cells." (PMID 33664415, 2021). "Anti-Glypican 3 (GPC3) CAR T cells expressing a soluble PD1 protein showed a superior antitumor effect against hepatocellular carcinoma." (PMID 34209505, 2021). "The prognostic significance of serum GPC3 levels and tumor cell GPC3 immunoreactivity in patients with hepatocellular carcinoma has been elucidated." (PMID 34926458, 2021). "The full-length form of GPC3 also assayed in blood samples correlated with tumoral GPC3 expression only in patients with HCV-induced liver carcinoma." (PMID 34065048, 2021). "Lastly, we noticed one shared integrated gene in the current CT3 CAR T cells targeting GPC2, PTPRA, which was also found in the CAR (hYP7) T cells targeting GPC3 in hepatocellular carcinoma from our previous study, although at different integration sites." (PMID 34195677, 2021). "Glypican-3 is a protein expressed in hepatocellular carcinoma with very limited expression on normal cells, and different trials have shown the feasibility and lack of toxicity of CAR-T cells targeting Glypican-3." (PMID 33874996, 2021). "Many studies have shown that GPC-3 promotes hepatocellular carcinoma cell proliferation by activating the classical Wnt signaling pathway." (PMID 34715880, 2021). "The CAR T cell membrane enabled the nanoparticles to target GPC3 on the surface of hepatocellular carcinoma cells in vitro and in vivo." (PMID 33833751, 2021). "IR780 nanoparticles were loaded on mesoporous silica, and subsequently coated with the membrane of CAR T cells specific to GPC3+ hepatocellular carcinoma." (PMID 33833751, 2021). "Accordingly, the authors co-expressed CXCR2 in glypican-3-targeting CAR T cells for enhanced hepatocellular carcinoma homing." (PMID 34885108, 2021). "GPC3 is overexpressed in hepatocellular carcinoma (HCC), embryonal tumours, melanoma, hepatoblastoma, and testicular germ-cell tumours, and it acts as a tumour oncogene." (PMID 34112123, 2021). "GPC3, glypican-3, is a heparan sulfate proteoglycan that is highly expressed in a variety of solid tumors, especially in hepatocellular carcinoma (HCC), while its expression is very low in normal adult tissues." (PMID 32999455, 2021).
hepatocellular carcinoma (continued). "GPC3, αFP, NY-ESO-1, SSX-2, human telomerase reverse transcriptase (hTERT), hepatocellular carcinoma-associated antigen-587 (HCA587), and melanoma antigen gene-A (MAGE-A) are some examples of such protein antigens." (PMID 34696292, 2021). "GPC3 influence several central signaling pathways in hepatocellular carcinoma and is also evaluated for CTC capture as described later." (PMID 32984308, 2020). "It has been reported that overexpression of GPC3 can promote the metastasis of hepatocellular carcinoma, but we found that it is expressed at low levels in PTC." (PMID 32766727, 2020). "AFP, Hepatocyte and GPC3 proteins are specific immunohistochemical factors for the diagnosis of hepatocellular carcinoma, while CK19 and CK7 are specific immunohistochemical factors for the diagnosis of cholangiocellular carcinoma." (PMID 32967689, 2020). "Antibody hGC33 to glypican-3, a membrane protein that is overexpressed on hepatocellular carcinoma cells, increased binding of sorafenib-loaded polyethylene glycol-b-PLGA polymer nanoparticles (hGC33-SFB-NP) to glypican-3 on the cancer cells." (PMID 33242103, 2020). "Up to now, Glypican-3 has been a reliable immunohistochemical marker for hepatocellular carcinoma diagnosis, and soluble Glypican-3 in serum has becoming a promising marker for liquid biopsy." (PMID 32127929, 2020). "One study proved in vitro and in vivo that by disrupting programmed death 1 receptor (PD-1) on the Glypican-3 (GPC3)-targeted second-generation CAR T-cells showed a much stronger activity against hepatocellular carcinoma." (PMID 31936611, 2020). "The mRNA expression of proliferation markers like GPC3 was significantly decreased in hepatocellular carcinoma cells (HepG2) during lectin protein-loaded chitosan-TPP nanoparticle treatment." (PMID 33145357, 2020). "Although this HCC marker was previously associated with poor prognosis, its specificity and overexpression in hepatoma cells have created an exciting opportunity to engineer specific CAR-T cells against GPC3-positive cell lines." (PMID 32784389, 2020). "GPC3 is the most extensively studied TAA in the production of CAR-T cells for hepatocellular carcinoma." (PMID 32784389, 2020). "Stronger GPC3 expression in the hepatocellular carcinoma would increase epithelial-mesenchymal transition of tumoral cells via interaction with the extracellular signal-regulated kinase (ERK) signaling pathway." (PMID 32582830, 2020). "Other GPCs have been shown to play roles in diseases such as hepatocellular carcinoma (GPC3;) and Simpson-Golabi-Behmel syndrome (GPC3/GPC4;)." (PMID 32398079, 2020). "Other isoforms, such as GPC3, -4 and -5, have been shown to interact with either Wnt ligands or growth factors and to mediate the migration of tumoral cells in breast, lung, and hepatocellular cancers." (PMID 32180897, 2020). "A recently conducted, phase II study of a vaccine for hepatocellular carcinoma directed toward GPC3 molecules reflected the potency of this treatment modality." (PMID 32784389, 2020). "GPC3 expression is down regulated in lung adenocarcinoma and clear cell renal carcinoma but overexpression occurs in hepatocellular carcinoma, ovarian clear cell carcinoma, melanoma, and neuroblastoma." (PMID 32582830, 2020). "The most prominent of these include glypican 3 (GPC3), alpha-fetoprotein (AFP), NY-ESO-1, SSX-2, human telomerase reverse transcriptase (hTERT), hepatocellular carcinoma-associated antigen-587 (HCA587), and melanoma antigen gene-A (MAGE-A)." (PMID 32784389, 2020). "GPC3 promotes the growth of hepatocellular carcinoma through the Wnt pathway and the activated extracellular signal-regulated kinase (ERK) pathway." (PMID 31199813, 2019). "We previously reported the identification of monocarboxylate transporter 4 (MCT4) and glypican-3 (GPC3) as prognostic factors for hepatocellular carcinoma (HCC), which are now considered significant poor prognostic factors for the disease." (PMID 31706332, 2019).